RUNX2 (RUNX family transcription factor 2)
Diseases named in the same sentence as RUNX2 in open-access papers (continued):
Sharing a sentence is not in itself a finding about the gene and the disease.
liver fibrosis (continued). "Taken together, our findings demonstrated that Runx2 is a crucial regulator participating in liver fibrosis by activating HSC." (PMID 37403784, 2023). "In this study, we found that Runx2 expression was significantly upregulated in human liver fibrosis with different aetiologies." (PMID 37403784, 2023). "Targeting RUNX2 with Vitamin D3 or CADD522 may represent promising therapeutic strategies for preventing liver fibrosis progression in CHB patients." (PMID 40287769, 2025). "Our findings suggest that targeting RUNX2 could be a potential therapeutic approach to mitigate liver fibrosis in chronic hepatitis B." (PMID 40287769, 2025). "RUNX2 promotes liver fibrosis in HBV-infected patients by upregulating ITGBL1 expression." (PMID 40287769, 2025). "Targeting Runx2 may represent a promising target for establishing therapeutic strategies for liver fibrosis." (PMID 37403784, 2023). "Previous studies showed that selective deletion of Itgav in HSC protected CCl4‐induced liver fibrosis, suggesting that Runx2 transcriptionally upregulating Itgav expression may be responsible for the progression of liver fibrosis in our study." (PMID 37403784, 2023). "Our data revealed a critical and yet unappreciated role of Runx2 in liver fibrosis and may provide a potential new therapeutic target for liver fibrosis." (PMID 37403784, 2023). "As a consequence, targeting the Runx2‐Itgav axis may be another choice of pan‐αv integrins inhibiting for liver fibrosis treatment." (PMID 37403784, 2023). "However, the specific role and underlying molecular mechanism of Runx2 during HSC activation and liver fibrosis remain elusive." (PMID 37403784, 2023). "Additionally, we found that Runx2‐specific overexpression in HSC enhanced CCl4‐induced liver fibrosis in mice by the injection of vitamin A‐coupled liposomes carrying Runx2 plasmid (VA‐Lip‐Runx2) or VA‐Lip‐Ctrl as well." (PMID 37403784, 2023). "Itgav encodes a major component of αv integrins, which are the key integrins in regulating TGF‐β1 activation and liver fibrosis progression, suggesting that Runx2 might activate HSC via Itgav signalling pathway." (PMID 37403784, 2023). "Collectively, our results strongly suggested that Runx2 directly upregulates Itgav expression by binding to its promoter, and activates the underlying signalling transduction, which in turn contributes to HSC activation and liver fibrosis progression." (PMID 37403784, 2023). "We also found that the level of Runx2 was higher in the individuals with advanced fibrosis stage, whereas lower in patients at early fibrosis stage, indicating that Runx2 expression was increased during progression of liver fibrosis." (PMID 37403784, 2023). "Knockdown of Runx2 in HSC markedly alleviated CCl4‐induced, 3,5‐diethoxycarbonyl‐1,4‐dihydrocollidine‐induced or methionine‐choline deficient (MCD)‐induced liver fibrosis, while hepatic overexpression of Runx2 via HBAAV‐Runx2 or VA‐Lip‐Runx2 injection exacerbated CCl4‐induced liver fibrosis." (PMID 37403784, 2023). "Additionally, Runx2 knockdown significantly alleviated CCl4‐induced liver fibrosis histologically with decreased collagen I deposition and HSC activation." (PMID 37403784, 2023). "Targeting RUNX2 may represent a promising therapeutic strategy for liver fibrosis." (PMID 40287769, 2025). "Therefore, combining antiviral therapy with RUNX2 inhibitors or Vitamin D3 supplementation may be a novel strategy to block the progression of liver fibrosis in CHB patients." (PMID 40287769, 2025). "Besides, overexpression of Runx2 did not spontaneously trigger HSC activation or independently cause liver fibrosis in vivo and in vitro, which is consistent with the previous research." (PMID 37403784, 2023). "Moreover, as hepatocytes (HCs) damage is an integral part of liver fibrosis, we generated HC‐specific Runx2 knockout mice (Runx2△/△HCs) by crossing Runx2ff mice with Alb‐Cre mice to verify whether Runx2 ablation in HCs affects the progress of liver fibrosis." (PMID 37403784, 2023).
liver fibrosis (continued). "Our results collectively establish that HBV promotes fibrosis through the RUNX2-mediated upregulation of ITGBL1, highlighting potential therapeutic targets for CHB-related liver fibrosis." (PMID 40287769, 2025). "More importantly, we found that Runx2 and α‐SMA were both markedly increased in non‐alcoholic steatohepatitis (NASH)‐related liver fibrosis induced by high‐fat diet treatment." (PMID 37403784, 2023). "Collectively, these findings suggested that Runx2 knockdown in HSC alleviates CCl4‐induced, DDC‐induced and MCD‐induced hepatic fibrosis." (PMID 37403784, 2023). "In the present study, we demonstrated that Runx2 was specifically expressed in the activated HSC in the liver, and played a critical role during the pathology of liver fibrosis." (PMID 37403784, 2023). "Therefore, our findings suggested that Runx2 activates HSC and promotes liver fibrosis mainly through Itgav." (PMID 37403784, 2023). "Blockade of Itgav attenuated Runx2‐induced HSC activation and liver fibrosis." (PMID 37403784, 2023). "Runx2 is critical for HSC activation via transcriptionally regulating Itgav expression during liver fibrosis, and may be a promising therapeutic target for liver fibrosis." (PMID 37403784, 2023). "Expectedly, HC‐specific deletion of Runx2 did not affect CCl4‐induced liver fibrosis." (PMID 37403784, 2023). "Notably, as blocking αv integrins could not fully rescue Runx2 overexpression accelerating liver fibrosis, we could not exclude the possibility that other downstream targets are involved in Runx2‐mediated HSC activation and liver fibrosis." (PMID 37403784, 2023).
nasopharyngeal carcinoma (6 papers, 2018 to 2024). A carcinoma arising from the nasopharyngeal epithelium. "RUNX2 upregulation was characterized as a downstream event of circRANBP17 in nasopharyngeal carcinoma." (PMID 37108164, 2023). "In nasopharyngeal carcinoma, RUNX2 overexpression abolished the effect of circRANBP17-dependent suppression on cancer cell invasion." (PMID 37108164, 2023). "The authors demonstrated circRanBP17 to promote nasopharyngeal cancer cell proliferation and invasion by acting via mir-635 and RUNX2 and pointed out circRanBP17 as a potential target for nasopharyngeal cancer treatment." (PMID 35850701, 2022). "In nasopharyngeal carcinoma, circRANBP17 was found to increase RUNX2 levels by sponging miR-635." (PMID 37108164, 2023). "In nasopharyngeal carcinoma, circRANBP17 promoted RUNX2 expression by sponging miR-635." (PMID 37108164, 2023).
papillary thyroid cancer (6 papers, 2011 to 2022). "Interestingly, in papillary thyroid cancer, the positive regulation of miR-218-5p and the inhibition of RUNX2 induce the inactivation of the PTEN/PI3K/AKT pathway; it is likely that this event occurs in CC." (PMID 35805994, 2022). "In addition, we show that the expression of Runx2 is upregulated in papillary thyroid cancer patient tissues compared to healthy normal thyroid tissues of the patients (Ee)." (PMID 36497320, 2022). "Interestingly, Runx2 and TAZ have been found over-expressed in thyroid papillary carcinoma and responsible for calcification processes present in these tumor tissues." (PMID 21966443, 2011).
uremia (6 papers, 2018 to 2022). A clinical syndrome associated with the retention of renal waste products or uremic toxins in the blood. "Vitamin D-mediated maintenance of aortic miR-145 content was associated with a 50% attenuation of uremia-induced reduction in α-actin and prevention of the increase in Runx2." (PMID 35807767, 2022). "Compared with the sham group, the Runx2 in the uremia group presented point accumulation, and the fluorescence intensity of Runx2 in the nucleus was significantly increased in uremic rats." (PMID 34398360, 2021). "In summary, these data suggest that gAd may inhibit VC in a rat model of uremia by inhibiting transcription factor Runx2 via inhibiting Wnt/β-catenin pathway." (PMID 34398360, 2021). "Therefore, we consider that gAd would balance the homeostasis of lipid metabolism of VSMCs, and subsequent the improvement of VC in uremia patients, possibly by reducing nuclear Runx2 activity via PI3k/AKT and Wnt/β-catenin signaling pathways." (PMID 34398360, 2021).
asthma (5 papers, 2007 to 2026). "Among the up-regulated genes were 3 associated with inhibition of proliferation (Gpnmb, Setd8, Runx2) and 1 promoting inflammatory and immune responses (Pik3cd), as well as 4 asthma-related genes (Arg1, Ccl24, Slc7a2, Mcpt1) identifiable only through qRT-PCR." (PMID 18087596, 2007). "In a mouse model of asthma, the overexpression of miR-30a-3p suppressed RUNX2 and HMGB1 and decreased eosinophilic inflammation." (PMID 36675299, 2023). "We found that RUNX2 transcript levels were significantly increased in bronchial brushings from asthma patients when compared with controls." (PMID 35093061, 2022). "RUNX2 expression was significantly increased in bronchial epithelium of asthma patients, IL‐13‐stimulated human bronchial epithelial cells and in OVA‐challenged mice airways." (PMID 35093061, 2022). "We conclude that epithelial miR-30a-3p could possibly target RUNX2/HMGB1 axis to suppress airway eosinophilic inflammation in asthma." (PMID 35093061, 2022). "Moreover, epithelial RUNX2 transcript levels in bronchial brushings were positively correlated with HMGB1 transcript levels in asthma patients." (PMID 35093061, 2022). "Epithelial miR-30a-3p could possibly target RUNX2/HMGB1 axis to suppress airway eosinophilia in asthma." (PMID 35093061, 2022). "Restoring RUNX2 may provide a new therapeutic approach for asthma." (PMID 41701118, 2026). "Therefore, epithelial miRNA-30a-3p could target the RUNX2/HMGB1 axis to reduce airway eosinophilia in asthma." (PMID 36675299, 2023). "There are three runt-related transcriptional factor (RUNX) genes, namely RUNX1, RUNX2, and RUNX3, as well as maternal smoking, which have been reported to potentially support the onset of asthma in children by increasing the expression of RUNX1." (PMID 36675299, 2023). "In support of RUNX2 as a target of miR‐30a‐3p, epithelial RUXN2 transcripts negatively correlated with miR‐30a‐3p expression in asthma patients." (PMID 35093061, 2022). "We demonstrated that, like RUNX2, HMGB1 expression was increased in bronchial epithelium of asthma patients, IL‐13‐stimulated human bronchial epithelial cells and OVA‐challenged mice airways." (PMID 35093061, 2022). "Immunofluorescent staining of bronchial biopsies revealed that the expression of RUNX2 and HMGB1 were both increased in the epithelial cells of asthma patients compared to controls." (PMID 35093061, 2022). "RUNX2 and HMGB1 expression was both enhanced in airway epithelium and was correlated with each other in asthma patients." (PMID 35093061, 2022).
clear cell renal cell carcinoma (5 papers, 2015 to 2023). "RUNX2 is related to a variety of tumors, particularly tumor invasion and metastasis, while the expression and molecular mechanisms of RUNX2 in clear cell renal cell carcinoma (ccRCC) keep to be determined." (PMID 36200301, 2023). "Our previous study has provided evidence that RUNX2 could regulate epithelial–mesenchymal transition in renal cell carcinomas, and RUNX2 was found to mediate tumor growth and metastasis in clear cell renal cell carcinoma." (PMID 36200301, 2023). "Mechanistically, previous studies have shown that ZIC2 is highly expressed in clear cell renal cell carcinoma (ccRCC) and promotes the proliferation and migration of ccRCC by regulating the expression of the downstream target gene Runx2 and the ZIC2/Runx2/NOLC1 signaling axis." (PMID 37479694, 2023). "Our TF family member analysis showed that RUNX1, RUNX2, and RUNX3 were all within the top 5 % of TFs correlated with hypomethylation of RUNX-containing enhancer probes in clear cell renal carcinoma (KIRC) a, b." (PMID 25994056, 2015).
oral squamous cell carcinoma (5 papers, 2022 to 2025). "As RUNX2 is a growth factor, systemic therapy should be avoided, and local application options should be considered, especially given the role of RUNX2 in neoplasms, particularly in oral squamous cell carcinoma." (PMID 39972547, 2025). "Fluorescence quantitative PCR (qPCR) was used to detect the expression of miR-23a-3p and Runx2 in human oral squamous cell carcinoma tissues and paracancerous tissues." (PMID 35342401, 2022). "A prior study has unveiled that GDF-10 through interaction with the transcription factor RUNX family transcription factor 2 can activate the TGFβRI/Smad3/ERK pathway in oral squamous cell carcinoma cells." (PMID 36714584, 2022). "Overexpression of miR-23a-3p or inhibition of Runx2 inhibited the malignant progression of oral squamous cell carcinoma CAL-27 and TSCCA." (PMID 35342401, 2022). "This study further examined the effect of Runx2 knockdown on the biological behavior of oral squamous cell carcinoma." (PMID 35342401, 2022). "CCK-8 assay and plate clone formation assay indicated that downregulation of Runx2 expression inhibited the growth and viability of oral squamous cell carcinoma cells." (PMID 35342401, 2022). "The expression of miR-23a-3p was downregulated in oral squamous cell carcinoma tissues, while the expression of Runx2 was upregulated." (PMID 35342401, 2022). "To further verify the targeted binding relationship between miR-23a-3p and Runx2 and its role in oral squamous cell carcinoma, we simultaneously transfected miR-23a-3p mimics and Runx2 overexpression plasmids and detected the changes in cells by CCK-8, Transwell, and clone formation assay." (PMID 35342401, 2022). "Western blot results showed that Runx2 expression was upregulated in oral squamous cell carcinoma." (PMID 35342401, 2022). "QPCR results showed that Runx2 expression was upregulated in oral squamous cell carcinoma." (PMID 35342401, 2022). "Mechanism studies suggest that the tumor-suppressive effect of miR-23a-3p may inhibit the malignant progression of oral squamous cell carcinoma by inhibiting the Runx2 regulation of PTEN/PI3K/Akt signaling pathway." (PMID 35342401, 2022). "In oral squamous cell carcinoma (OSCC), RUNX2 RNA levels were found to be statistically higher in tumor tissues than in normal tissues by qRT-PCR analysis of 40 pathological specimens." (PMID 37108164, 2023). "RUNX2 was shown to be an interactive target of miR-23a-3p in CAL-27 cells and TSCCA cells, and oral squamous cell carcinoma (OSCC) overexpressing miR-23a-3p mimics decreased the RUNX2 level." (PMID 37108164, 2023). "The coexpression correlation results showed that there was a negative coexpression correlation between miR-23a-3p and Runx2 in oral squamous cell carcinoma." (PMID 35342401, 2022).
prostate adenocarcinoma (5 papers, 2012 to 2024). "RUNX1 and RUNX2 had similar cancer expression profiles, with overexpression in most cancer types and downregulation in prostate adenocarcinoma (PRAD)." (PMID 39822248, 2024). "RUNX1, RUNX2, and RUNX3 were all highly correlated with immune cell infiltration in the HNSC, KIRC, LGG, liver hepatocellular carcinoma (LIHC), and prostate adenocarcinoma (PRAD)." (PMID 36321611, 2023). "Likewise, we detected predominant localization of phosphorylated RUNX2 and Smad 5 in the nuclei of lysates made from PC3 cells, prostatic adenocarcinoma and in tissue microarray sections containing primary prostatic tumor (grade 2–4)." (PMID 22966907, 2012).
prostate tumor (5 papers, 2012 to 2021). "In response to Lrp5-overexpressing MSC CM, TRAMP prostate tumor cells also reduced EdU-based proliferation, transwell-based invasion, downregulated tumorigenic genes such as Lrp5, Runx2, MMP9 and Snail." (PMID 33859739, 2021). "Further, Runx2 is reported to be expressed in nearly 50% of patients with primary prostate tumors or PCa-induced bone metastases." (PMID 27634876, 2016). "Mutation of three residues in RUNX2 leading to impaired recruitment of SMADs to RUNX2 subnuclear foci reduces prostate tumor size and osteolytic disease in the intratibial model." (PMID 26204939, 2015). "On the contrary, miR-203-3p is progressively downregulated in primary prostate tumors, is absent or lowly expressed in bone metastatic PCa cells and metastases, and suppresses Runx2 and other genes that promote PCa metastasis to bone." (PMID 27634876, 2016). "The presence of miRNAs targeting Runx1 and/or Runx2 in normal prostate tissue and the complete absence of these miRNAs in prostate tumors upregulates both Runx1 and Runx2 as well as AKT signaling." (PMID 27634876, 2016).
renal cell carcinoma (5 papers, 2020 to 2025). "RUNX2 expression was associated with adverse overall survival in a study of 301 renal cell carcinoma patients." (PMID 37108164, 2023). "Zic2 was required for RUNX2′s high expression in renal cell carcinoma." (PMID 37108164, 2023). "Relatively high RUNX2 levels were detected by IHC staining in tissues of renal cell carcinoma compared with nontumor tissue, whose regulatory mechanism required Zic family member 2 (Zic2) in 786-O and ACHN cells." (PMID 37108164, 2023).
respiratory failure (5 papers, 2014 to 2024). The significant impairment of gas exchange within the lungs resulting in hypoxia, hypercarbia, or both, to the extent that organ tissue perfusion is severely compromised. "Runx2 homozygous defective mice die soon after birth due to respiratory failure, with impaired mesenchymal osteoblast development, which results in the absence of osteocytes and bones." (PMID 39408869, 2024). "On the other hand, Runx2 is indispensable for bone development, as evidenced by Runx2-/- mice which lack ossified skeleton and therefore die from respiratory failure shortly after birth." (PMID 24699678, 2014). "RUNX2 plays a critical role in the differentiation of osteoblasts and chondrocytes, and mice lacking functional Runx2 alleles perish shortly after birth as a result of impaired ossification and respiratory failure." (PMID 39822248, 2024). "Mice lacking Runx1 die as embryos from hematopoietic failure and mice lacking Runx2 exhibit neonatal lethality from respiratory failure." (PMID 36766843, 2023).
squamous cell carcinoma (5 papers, 2011 to 2025). A carcinoma arising from squamous epithelial cells. "This is particularly relevant in cases where RUNX2 rearrangements or IRF2BP2::RUNX2 fusion have been identified, as seen in studies of primary squamous cell carcinoma of the parotid, where certain cases were later reclassified as keratocystoma or squamous cell carcinoma ex-keratocystoma." (PMID 40217739, 2025). "The role of SNAI2 downstream of Runx2 in BCa is reminiscent of the role of its homologue, SNAI1, in EMT and metastasis of breast, ovarian, colon, lung and squamous cell carcinomas." (PMID 22151997, 2011). "Runx2 expression was upregulated in squamous cell carcinoma cells (CAL-27, TSCCA, TCA8113, and SCC-9) compared with normal oral keratinocytes (NHOK)." (PMID 35342401, 2022).
tendinopathy (5 papers, 2019 to 2023). "Additionally, CHD9 has been implicated in upregulating RUNX2 which may shed light on tendinopathy-associated ectopic ossification." (PMID 37821884, 2023). "To investigate the effect of nesfatin-1 on HO in tendinopathy, we detected the expression of osteogenic markers such as COL1A1, ALP, and RUNX2, under nesfatin-1 stimulation in vitro." (PMID 33344440, 2020). "We identified a Runx2 inhibitor, AGA, which blocks the osteogenic differentiation of TDSCs from chemically induced tendinopathy, and a PPARγ antagonist, T0070907, that inhibits the adipogenic differentiation of TDSCs from injury-with-overuse tendinopathy." (PMID 32294907, 2020). "The expression of Pparg was higher in the collagenase-induced tendinopathy sample treated with saline injection than in the control group (p < 0.05), but the expressions of the type I and type III collagen genes, Runx2 and Sox9 were similar between the saline-treated and control groups." (PMID 30886307, 2019).